IFNG (interferon gamma)
Diseases named in the same sentence as IFNG in open-access papers (continued):
Sharing a sentence is not in itself a finding about the gene and the disease.
depression (continued). "An association between elevated levels of proinflammatory cytokines and the development of psychiatric disorders, such as depression, was first observed in hepatitis C patients treated with interferon gamma (IFN-γ) for therapeutic purposes." (PMID 37064799, 2023). "The treatment normalized brain levels of IL-1β, TNFα, and IFNγ which were higher in depression models." (PMID 37240605, 2023). "Second, important inflammatory mediators such as interferon gamma and IL-6, which induce increasing gut permeability termed “leaky gut,” are significantly increased in patients with depression." (PMID 36275822, 2022). "Depression increases the production of several inflammatory cytokines, including IL-1, IL-6, and interferon-gamma." (PMID 34711196, 2021). "In people with MS and comorbid fatigue and/or depression there is reported increased serum and cerebrospinal fluid (CSF) concentration of proinflammatory cytokines, interleukins, interferon γ (IFNγ), and neopterin." (PMID 35242093, 2021). "In patients with depression and AD raised levels of pro-inflammatory cytokines, acute phase proteins (APPs), interferon gamma (IFN-γ), interleukin 1 (IL-1), IL-6, and TNF-α were observed." (PMID 34573069, 2021). "Another animal model of depression, the chronic mild stress procedure significantly increased IFNγ and IDO mRNA and decreased KAT II mRNA in the rat cortex." (PMID 34072767, 2021). "Based on the univariate analysis of the GLM, we found significant differences in the years of education, cytokines (IL-1β, IL-2, IL-6, IL-12p70, IL-17A, IFNγ, TNFα, IL-10, and IL-13), and depression severity (indicated by the PHQ) among the groups." (PMID 32703187, 2020). "In a more recent, larger scale meta-analysis a greater range of changes have been described in people with depression, including higher levels of TNFα, IL-6, IL-13, IL-18, IL-12, IL-1RA, and sTNFR2, along with a decrease in the proinflammatory cytokine IFNγ." (PMID 31379879, 2019). "Other findings indicate higher levels of TNFα and IFNγ in in vitro-stimulated CD8+ T cells isolated from patients with depression and IFNγ levels correlate with the severity of the condition." (PMID 31379879, 2019). "Increased expression of pro-inflammatory cytokines IL-1β, IL-6, TNF-α, as well as interferon gamma (IFN-γ), and C-reactive protein (CRP) is repeatedly observed in patients suffering from depression and has been associated with specific symptoms of depression." (PMID 28239408, 2017). "For example, there is evidence to suggest that pre-operative C-reactive protein levels predict depression experienced 6 months after CABG surgery and interferon-gamma measured in the days following surgery predicts depression 12-months after surgery." (PMID 27281345, 2016). "Meanwhile, some studies found that in patients with severe depressive disorder, the activation of proinflammatory cytokines and inhibition of interferon-gamma, interleukin-2, and interleukin-4 were documented." (PMID 27955661, 2016). "Since IFNG (+874) gene encodes the production of IFNG, the strongest inducer of IDO, we suggested that IDO activity is a risk factor for IFN-alpha – associated depression." (PMID 25346938, 2014). "In depression there is an increase in pro-inflammatory cytokines (interleukine-1β (IL- 1β); IL-6, and IFNγ (interferon-gamma)) and the acute phase of depression is due to high levels of pro-inflammatory cytokines such as IL-6 and IL-1β." (PMID 23204984, 2012). "A cluster of cytokines including interleukin-1 beta (IL-1β), IL-2, IL-6, interferon-gamma, and tumor necrosis factor alpha (TNFα) have been reported to correlate with depression symptoms." (PMID 21864357, 2011). "We have already established that development of inflammation-associated depression is dependent on activation of the tryptophan degrading enzyme indoleamine 2,3 dioxygenase (IDO) by proinflammatory cytokines such as IFNγ and TNFα." (PMID 21810259, 2011).
depression (continued). "However, a more nuanced understanding shows that other cytokines, such as interleukin-10 (IL-10) and interferon-gamma (IFN-γ), also play significant roles in the neuroinflammatory processes associated with depression." (PMID 40305200, 2025). "A recent study suggests that Lactobacillus may help alleviate depression and anxiety induced by chronic stress by sustaining levels of interferon gamma (IFN-γ)." (PMID 38919504, 2024). "Last, but not least, we aimed to explore whether alterations of immune activation and interferon-gamma (IFN-γ) mediated pathways- which have been shown earlier to be related to depression, impaired quality of life, and fatigue might be involved." (PMID 37233680, 2023). "In addition, BD patients in remission after the depression had higher interferon-gamma (IFN-γ) concentrations than healthy people and patients in sustained remission." (PMID 37662097, 2023). "Moreover, pro-inflammatory cytokines such as IL-1β and IL-6 are increased in the serum of patients with depression and interferon gamma (IFN-γ) is increased in bipolar disorder." (PMID 36875655, 2023). "Moreover, recent evidence indicated that depression is related to serum upregulation of proinflammatory cytokines, including IFNγ." (PMID 37530884, 2023). "Interferon gamma (INF-γ) is also indicated to play a role in depression." (PMID 36077051, 2022). "Moreover, depression, pain, and other neurological manifestations of SS are related to interferon-gamma inducible kynurenine metabolic pathway activity." (PMID 34723755, 2021). "Pro-inflammatory cytokines such as Interferon-gamma (IFNγ) and Tumor necrosis factor α (TNFα) might contribute to the development of depressive disorder by regulating neuronal excitability, synaptic transmission, synaptic plasticity, and neuronal survival." (PMID 34206086, 2021). "Pro-inflammatory cytokines such as IFNγ and TNFα might induce the development of depressive disorder by affecting neuronal excitability, synaptic transmission, synaptic plasticity, and neuronal survival." (PMID 34206086, 2021). "Numerous studies have reported that circulating pro-inflammatory cytokines, such as interleukin-1 beta (IL-1β), IL-6, interferon gamma (IFN-γ), and tumor necrosis factor alpha (TNF-α), may be associated with some forms of major depression." (PMID 26521132, 2015). "The increased frequency of high producer (T) allele of IFN-gamma (IFNG) (+874) gene, that encodes IFNG production, in depressed patients suggested that increased IDO activity might be a risk factor for depression." (PMID 25346938, 2014). "Such dissociation was also found with cancer patients wherein paroxetine, a SSRI class anti-depressant, had little activity against neurovegatative symptoms of sickness following IFNγ treatment, whereas symptoms of depression were more responsive to paroxetine." (PMID 21306618, 2011). "However, cytokines like IL-10 and interferon gamma yield inconsistent patterns across studies, suggesting that inflammation in depression may vary significantly between subtypes or individuals." (PMID 40428308, 2025). "Evidence from both adult and pediatric populations suggests that depression is linked to alterations in immune function, particularly involving pro-inflammatory cytokines such as interleukin-6 (IL-6), interleukin-1β (IL-1β), tumor necrosis factor-alpha (TNF-α), and interferon-gamma (IFN-γ)." (PMID 40563330, 2025). "Furthermore, IL-6, tumor necrosis factor-alpha (TNF-α), and IL-1β are implicated in the pathophysiology of depression, and individuals with depression often have elevated circulating IL-1β, IL-6, and TNF with reduced levels of interferon-gamma (IFN-γ), IL-10, and IL-4." (PMID 35546876, 2022). "Pro-inflammatory cytokines such as interferon-gamma (IFNγ) and tumour necrosis factor-alpha (TNFα) might affect the progress of depressive disorder by regulating neuronal excitability, synaptic transmission, synaptic plasticity, excitotoxicity and neuronal survival." (PMID 33322180, 2020).
depression (continued). "IL-1, TNFα, IFNγ, NGF, or microglia activation in depression, as well as IL-4, TNFα, and IL-10 in mania, were normalized by celecoxib in preclinical studies." (PMID 37240605, 2023). "A recent study found elevated levels of IL-2, IL-6, and interferon-gamma (IFN-γ) in patients suffering from co-morbid COPD and depression compared to healthy controls, though the implications of these findings remain uncertain." (PMID 37754012, 2023). "For instance, preclinical studies have demonstrated positive results regarding central IFNγ and NGF for depression, as well as peripheral IL-10 for mania." (PMID 37240605, 2023). "BifidobacteriumpseudocatenulatumCECT7765 can also ameliorate MS-induced gut inflammation (decreased interferon-gamma, IFN-γ), which improves depression-like behaviors." (PMID 34890365, 2021). "Chronic social defeat depression mouse model led to increased plasma levels of TNF-α in parallel with KYN, 3-HK, and KYNA as seen with IFNγ." (PMID 34072767, 2021). "The inflammatory etiology of fatigue and depression in MS was supported by evidence of increased serum and CSF concentration of inflammatory mediators such as TNF, interleukins (IL-1a, IL-1b, IL-6), IFNγ, and neopterin." (PMID 35242093, 2021). "High IFNγ and IL10 also predicted better HADS “depression” outcome, albeit with lower R2 than TNFα in the confounder controlled model (not shown)." (PMID 33240126, 2020). "People who suffer from depression have increased concentrations of inflammatory state markers, such as interleukin 6 (IL-6), tumor necrosis factor-alpha (TNF-α), and other interleukins, while interferon-gamma (IFN-γ) levels are decreased." (PMID 38732635, 2024). "Cytokines, such as interferon-γ (IFNγ), C-reactive protein (CRP) and IL-6, increase with chronic stress, correlate with the severity of depression and predict cognitive changes in depression." (PMID 37836393, 2023). "Second, the pathogenesis of POI with anxiety or depression may be relevant to the levels of transforming growth factor-β (TGF-β) and interferon gamma (IFN-γ)." (PMID 36705738, 2023). "On the other hand, not only proinflammatory cytokines, e.g. tumor necrosis factor-alpha – (TNF-α), the interleukins (IL) and interferon-gamma (IFN-gamma), but also anti-inflammatory cytokines are released by CNS and peripheral-derived immune cells and play a powerful role in depression." (PMID 25880127, 2015).
rheumatoid arthritis (246 papers, 2004 to 2026). A chronic, systemic autoimmune disorder characterized by inflammation in the synovial membranes and articular surfaces. "In a recent study on the genetics of PD and rheumatoid arthritis, an allele of the interferon-gamma gene was identified as a significant disease-specific marker common to both diseases." (PMID 33138320, 2020). "The A allele of rs2430561 in IFNγ was indicative for severe periodontitis among the patients with rheumatoid arthritis (p = 0.039)." (PMID 30890897, 2019). "1,25-dihydroxyvitaminD3 (1,25(OH)2D3), has potent anti-inflammatory effects, including suppression of IL-17 + and IFNγ+ T cells implicated in rheumatoid arthritis (RA), but efficacy at the site of active disease is unclear." (PMID 29066221, 2018). "Finally, probably due to their ability to secrete both IL-17 and IFNγ, γδT17 cells have also been implicated in autoimmune disorders, such as rheumatoid arthritis (RA) or experimental autoimmune encephalomyelitis (EAE)." (PMID 28708082, 2017). "Rheumatoid arthritis (RA) is characterized by chronic inflammation driven by pro-inflammatory cytokines such as interleukin-6 (IL-6) and interferon-gamma (IFN-γ), which activate intracellular JAKs through immune cell receptors." (PMID 40677425, 2025). "Elevated levels of IL-6, IL-18, IFNγ, IL-17, IL-23, and TNFα have been found in the serum of patients with rheumatoid arthritis, as well as psoriatic arthritis." (PMID 40170117, 2025). "IL-7 has been found to effectively stimulate the production of IFNγ and TNFα in rheumatoid arthritis and IL-17 in spondyloarthritis." (PMID 37047315, 2023). "GSK-J4 has been shown to inhibit IFNγ production in NK cells isolated from the synovial fluids of treatment-naïve rheumatoid arthritis patients." (PMID 35915507, 2022). "IL-18, together with IL-12, induces high levels of IFNγ production by T cells, and its expression correlates with disease activities of rheumatoid arthritis and Crohn’s disease." (PMID 35626130, 2022). "The synovial joints of rheumatoid arthritis patients are enriched in pro-inflammatory NK cells, which release copious amount of IFNγ in response to IL-15 stimulation and support the formation of bone-resorbing osteoclasts to promote bone erosion." (PMID 35915507, 2022). "This is in contrast to adult SpA where lower levels of IFNγ are found in the synovium compared to those with rheumatoid arthritis and studies suggest dysregulation of IFNγ genes." (PMID 34136509, 2021). "One study showed that Th17 T cells within inflamed joints of rheumatoid arthritis patients had gained expression of IFNγ (and lost expression of IL-17)." (PMID 34925371, 2021). "And indeed, the T cell-mediated increased IFNγ expression induced by periodontal infections with P.g. or Aggregatibacter actinomycetemcomitans was shown to be promoting rheumatoid arthritis." (PMID 30890897, 2019). "Finally, Jones and colleagues reported in their study with AIA rats that MG-132 inhibited the MMP-2 activity induced by the combination of TNFα and IFNγ in rheumatoid arthritis synovial fibroblasts (RASFs)." (PMID 40243560, 2025). "A recent study did a comparative analysis of synovial tissue from patients with LA, rheumatoid arthritis, and low inflammation osteoarthritis and found that LA is unique, showing elevated levels of IFN-γ and IFNγ-producing T cells and NK cells in synovial fluid." (PMID 34485323, 2021). "In addition to these pathways, lung fibrosis, keratinization/cornification, rheumatoid arthritis, and negative regulation of interferon-gamma production pathways were also significantly upregulated." (PMID 32698440, 2020). "Also, patients with rheumatoid arthritis were shown to exhibit higher levels of IFNγ in mononuclear cells and tissues from affected organs." (PMID 30890897, 2019). "Rheumatoid arthritis synovial macrophages exhibit characteristics of IL10- or IFNγ-stimulation." (PMID 31921150, 2019).
rheumatoid arthritis (continued). "Polarizing cytokines such as IFNγ might contribute to the high levels of Flt3 ligand found in rheumatoid arthritis synovium by shifting the Mphi polarization into a M1 phenotype." (PMID 29854425, 2018). "Dysfunctional CD46 signalling might also be implicated in the pathogenesis of rheumatoid arthritis (RA), where CD4+ T cells have a defect in the shutdown of IFNγ production following CD46 co-stimulation." (PMID 27739531, 2016). "Given their capacity to produce a variety of cytokines (IL4, IL21 and IFNγ), their association with ACPA positive RA and their presence in the synovium, we suggest an important role of double positive T cells in the pathogenesis of rheumatoid arthritis." (PMID 24667579, 2014). "Data from randomized controlled trials have shown that IFNγ does not prevent bone loss in rheumatoid arthritis." (PMID 23935650, 2013). "In humans IFNγ is positively correlated with bone erosions in leprosy and rheumatoid arthritis." (PMID 23935650, 2013). "Recently in an experimental model of rheumatoid arthritis (RA), it has been shown that MHC alleles that drive disease are associated with a T helper cell type 1 (Th1) response with secretion of interferon-gamma (IFN-γ)." (PMID 28386263, 2017). "Interferon-gamma (IFN-γ) is overexpressed in rheumatoid synovium and thought to be involved in the pathogenesis of rheumatoid arthritis (RA)." (PMID 34895310, 2021). "In rheumatoid arthritis, TSP-2 suppressed the production of interferon-gamma and tumor necrosis factor-alpha, and induced the depletion of tissue-residing T-cells." (PMID 24376766, 2013). "Recently, an in vitro cell culture study with human myofibers using interferon gamma (IFN-γ)-induced muscle wasting corroborated the use of tofacitinib and baricitinib (JAK/STAT inhibitors), two commonly prescribed therapeutics for rheumatoid arthritis (RA), which fully hindered muscle atrophy." (PMID 36080280, 2022). "Moreover, IFNγ‐induced PD‐L1 expression is blocked by tofacitinib, which is a JAK‐STAT inhibitor broadly used in the treatment of rheumatoid arthritis." (PMID 33491334, 2021). "Natural killer cells in rheumatoid arthritis patients were reduced upon IFX therapy and in ulcerative colitis patients derived cells, IFX treatment decreased the proliferation of CD4+ and CD8+ T-cells as well as their secretion level of IFNγ and TNFα, among other cytokines." (PMID 31272418, 2019). "Rheumatoid arthritis (RA) was supposed to be a Th1 disease; however, both sensitive and specific radioimmunoassays and a standard cytopathic inhibition assay showed little or no IFNγ in synovial fluids." (PMID 28698517, 2017). "In rheumatoid arthritis (RA), CD36 expression in fibroblasts is increased by macrophage-derived inflammatory mediators, including interleukin-1β (IL-1β), IL-6 and interferon gamma (IFN-γ)." (PMID 37576819, 2023). "In rheumatoid arthritis, the CD4+CXCR3+CCR6+ subset is known to express high levels of IFNγ with poor secretion of IL-17A,36 though we did not observe any associated cytokine profile in our remission patients." (PMID 31540934, 2019). "Th17/Th22 (CXCR3−CCR4+), Th17.1 (CXCR3+CCR4−), DP (CXCR3+CCR4+), and DN (CXCR3−CCR4−) CCR6+ memTh, cells sorted from PBMC of healthy donors or treatment-naïve early rheumatoid arthritis (RA) patients, were cocultured with SF from RA patients with or without anti-IL17A, anti-IFNγ, or 1,25(OH)2D3." (PMID 34082814, 2021).